SMAD3 (SMAD family member 3)
Diseases named in the same sentence as SMAD3 in open-access papers (continued):
Sharing a sentence is not in itself a finding about the gene and the disease.
lung carcinoma (continued). "SMAD3 also promotes lung cancer progression by influencing downstream factors." (PMID 37685308, 2023). "Moreover, the long noncoding RNA HCP5 induced by SMAD3 regulates lung adenocarcinoma metastasis by sponging miR-203, implying that SMAD3 is a main target molecule for the inhibition of lung cancer metastasis." (PMID 37121971, 2023). "In this study, by resolving the transcriptome dynamics of neutrophils in the TME at a single-cell resolution, we demonstrate that Smad3 induces polarization of TAN to a predominant N2 state in lung cancer, whereas deletion of Smad3 induces polarization to an N1 state." (PMID 37002229, 2023). "Emerging evidence indicates the importance of Smad3 in lung cancer TME." (PMID 37002229, 2023). "Therefore, we examined the regulatory role of Smad3-dependent TME in MNT in the experimental lung cancer models." (PMID 36206343, 2022). "Moreover, Pfn2 correlates with SMAD3 expression in human lung cancers, where its overexpression promotes lung cancer growth and metastasis." (PMID 33672325, 2021). "Importantly, restoration of KDM4C partially rescued the reduced levels of TGF-β2, p-Smad2 and p-Smad3 in USP9X-depleted lung cancer cells, suggesting that USP9X silencing inhibits TGF-β2/Smad signaling in a KDM4C-dependent manner." (PMID 33558705, 2021). "Interestingly, we also noticed that the regions of identified H3K27ac peaks in H1299 cells highly coincide to the SMAD3 ChIP-seq peaks in the lung cancer A549 cell line, suggesting a common SMAD3 autoregulatory loop." (PMID 34580281, 2021). "We have recently reported that AA is a Smad7 agonist and NG is a Smad3 inhibitor in lung carcinoma." (PMID 34514726, 2021). "Since CSC treatment downregulates Smad3 by promoting miR-216b expression, we reasoned that induction in miR-216b function might upregulate BCL-2 by reducing Smad3 expression and increase chemoresistance of lung cancer cells." (PMID 32668597, 2020). "Meanwhile, some studies have focused on uncovering the correlation between SMAD3 and lung cancer." (PMID 30594196, 2018). "Furthermore, we also observed that EP treatment resulted in the reduced protein expression of Smad2 and Smad3, which are important for lung cancer growth and metastasis." (PMID 30560887, 2018). "Previous research demonstrated that HDAC1, a histone deacetylase, could bind to Smad3 promoter region in lung cancer cells to suppress Smad3 expression in human lung cancer cells." (PMID 28598443, 2017). "By contrast, Smad3+/+ mice developed massive lung cancer with a 100% mortality rate." (PMID 28262747, 2017). "Interestingly, it can also act as an anti-tumor immunotherapeutic agent thanks to its inductive effect on Smad7 in combination with naringenin (Smad3 inhibitor), which increases the ability of NK cells to inhibit the progression of invasive melanoma and lung carcinoma in animal models and in vivo." (PMID 38610995, 2024). "In addition, kaempferol (10, 25, 50 μM) treatment of A549 lung cancer cells, followed by TGFß‐1 stimulation, resulted in phosphorylation of Smad3 (although phosphorylation at residue Thr179 was down‐regulated) and the formation and nuclear translocation of Smad4 complexes." (PMID 37697969, 2023). "Therefore, Smad3 may represent a potential therapeutic target for enhancing N1 anticancer immunity in lung cancer." (PMID 37002229, 2023). "Here, we found that the histone methyltransferase SMYD2 is overexpressed in lung cancer and that knockdown of SMYD2 could reduce the rates of cell migration and invasion in lung cancer cell lines via direct downregulation of SMAD3 via SMYD2-mediated epigenetic regulation." (PMID 37121971, 2023). "Thus, in this study, we hypothesized that SMYD2 was overexpressed in lung cancer and identified SMAD3 as a direct target of SMYD2 via epigenetic regulation that promotes lung cancer metastasis." (PMID 37121971, 2023).
lung carcinoma (continued). "Moreover, it is necessary to determine whether the radiosensitivity is also affected by the mutations of SMAD3 or SMAD4 in other cancers, such as nasopharyngeal carcinoma and lung cancer." (PMID 34434896, 2021). "To investigate whether miR-216b can increase BCL-2 expression and promote resistance of lung cancer cells to anti-cancer drugs by downregulating Smad3 expression, we established NCI-H460 human NSCLC cell clones by stably expressing miR-216b using lentiviral vector plenty-III-GFP pri-mir-216b." (PMID 32668597, 2020). "Thus, SMAD3 promotes the progression of nonsmall cell lung cancer by upregulating PAX6 expression." (PMID 30594196, 2018). "Therefore, Smad3-related miR-206 and miR-140 could effectively inhibit lung cancer cell metastasis in vitro and in vivo." (PMID 28005074, 2016). "We have previously shown that SKI and SnoN oncoproteins cooperate with phosphorylated STAT3 in an adenocarcinoma lung cancer cell line, HCC827, to repress transcription of the Smad3 gene, which renders the sensitive cells resistant to gefitinib." (PMID 38960622, 2024). "Firstly, the precise targeting and regulation of molecules such as SMAD3 and ITGA6 in patients with lung cancer remains relatively challenging given the current technological level." (PMID 38493128, 2024). "LncRNA Smyca functions as a scaffold and facilitates the binding of Smad3 and Smad4, which promotes TGF-β/Smad signaling-mediated EMT and lung cancer cell migration." (PMID 38818471, 2024). "The present results showed that SMAD3 expression was significantly upregulated and correlated with YAP in lung cancer patients." (PMID 38589525, 2024). "In lung cancer, profiling-2 and ACP5 regulate Smad2 and Smad3 expression for lung cancer growth and metastasis, and miR-15a and miR-32-5p directly regulate SMAD3 expression for lung cancer metastasis." (PMID 37121971, 2023). "In summary, SMAD3, one of the key mediators of the TGF-β pathway, plays a crucial role in lung cancer progression by influencing the tumour microenvironment or assisting other oncogenes." (PMID 37685308, 2023). "MiR‐133a inhibits lung cancer cell proliferation in vivo and in vitro by targeting the LASP1 and TGF‐β/Smad3 signaling pathways." (PMID 36305754, 2023). "Our results indicate that SMAD3 is not a direct target of miR-203, despite the decreased protein expression of SMAD3 in TSCCLN#5 cells transfected with the miR-203 mimic, although SMAD3 has been suggested to be a target of miR-203 in human lung cancer." (PMID 37601756, 2023). "Among them, miR-145 directly targets SMAD3, a key transcription factor involved in TGF-β responses, which has been confirmed in lung cancer." (PMID 35205713, 2022). "Through the MAPK pathway or the TGF-beta/Smad3 pathway, AHNAK2 promoted lung cancer progression, which involves cell proliferation, migration, invasion, and epithelial–mesenchymal transition." (PMID 36091120, 2022). "Expression of PFN2 induced the transactivation of Smad2 and Smad3, and these transmission factors enhanced TGF-β-induced EMT and angiogenesis in lung cancer." (PMID 35327465, 2022). "Via reduced phospho-Smad3/Smad3, miR-206 and miR-140 downregulate TRIB2 to further suppress lung cancer cell proliferation and metastasis." (PMID 35790734, 2022). "Other research revealed that CALR regulated EMT through modulating Smad signaling and calcium signaling in lung cancer cells and via TGF-β/Smad3/NRP1 pathway in nasopharyngeal carcinoma cells." (PMID 35641480, 2022). "EGFRex19 and KRASG12C cancer cell clusters displayed differential enrichment in lung cancer signatures, proliferation signatures, epithelium development, and TGF-β signaling through SMAD2 and SMAD3, when compared to other epithelial clusters." (PMID 33712615, 2021). "TGF-β/Smad3 signaling plays critical roles in biological processes, such as epithelial-mesenchymal transition (EMT) lung cancer cell progression and lung cancer patient survival." (PMID 34307117, 2021).
lung carcinoma (continued). "In conclusion, miR‐133a acted as a tumor suppressor in lung cancer progression by regulating the LASP1 and TGF‐β/Smad3 signaling pathway." (PMID 33074595, 2020). "Knockdown of SMAD3 attenuated the TGF-β-induced HSP27 expression and enhanced the chemosensitivity of human lung cancer to cisplatin." (PMID 32982740, 2020). "Another regulation of Smad2/3 proteins showed that profilin-2 interacts with HDAC1 to inhibit the binding of HDAC1 to the promoters of Smad2 and Smad3, leading to their activation and enhancing the TGF-β-induced EMT and angiogenesis in lung cancer cells." (PMID 32114978, 2020). "In human lung cancer cells, EGCG inhibits TGF-β1-mediated EMT by suppressing the acetylation of Smad2 and Smad3." (PMID 31311401, 2019). "For example, the lncRNA LINC01186, which inhibits migration and invasion via epithelial-mesenchymal transition (EMT) in lung cancer, is regulated by TGF-β/Smad3." (PMID 31281667, 2019). "Some previous study indicated that IL-6/STAT3 signal was required for TGF-β-induced EMT process in lung cancer cells, and the crosstalk between the IL-6/STAT3 and TGF-β/p-SMAD3 signaling pathway did exist in certain conditions." (PMID 27992365, 2017). "Among 427 genes reported in the first study as being differentially expressed in subjects with lung cancer are included 11 of our smoking-related DEGs and 18 DMGs, including hub genes ADM and SMAD3." (PMID 26837704, 2016). "Lung cancer cells also promote M2 polarization of TAMs, and the secretion of TGF-β by TAMs activates the c-Jun and Smad3 pathways in lung cancer cells, leading to increased expression of SOX9, thereby facilitating epithelial-mesenchymal transition (EMT), tumor proliferation, migration, and invasion." (PMID 40787464, 2025). "Lung cancer regulatory networks from trametinib-treated cells confirmed the strong involvement of the RAS-ERK signaling pathway and its positive influence on ETS1, FOSL1 and SMAD3." (PMID 41184222, 2025). "Additionally, M2 macrophages can also secrete TGF-β to induce Sox9 expression in lung cancer cells through the c-Jun/Smad3 pathway, thereby inducing EMT and enhancing lung cancer cell migration." (PMID 38840908, 2024). "Furthermore, SMYD2 regulates lung cancer metastasis by directly controlling SMAD family member 3 (SMAD3), which regulates the progression of lung cancer." (PMID 39482529, 2024). "In addition to SMAD3, SMAD4 and SMAD7 are also involved in a range of biological behaviours in lung cancer." (PMID 37685308, 2023). "By contrast, neutrophils in the TME in Smad3-KO mice contained a low proportion of N2 and a high proportion of N1 phenotype cells, implying a role for Smad3 in the N1/N2 polarization of TAN in lung cancer." (PMID 37002229, 2023). "Thus, we suggest that downregulation of SMAD3 by SMYD2 knockdown strongly affects the migration and invasion of lung cancer cell lines." (PMID 37121971, 2023). "In lung cancer cell lines, histone methyltransferase SMYD2 promoted invasive metastasis by reducing the distribution of H3K4me1 in the SMAD3 promoter region and promoting SMAD3 expression." (PMID 37685308, 2023). "Taken together, our results identify Smad3 as a regulator of neutrophil N1/N2 polarization within the TME and demonstrate that Smad3 is a druggable target to enhance neutrophil-mediated antitumor activity in lung cancer." (PMID 37002229, 2023). "Consistently, we further demonstrated that both macrophage-specific and pharmaceutical inhibition of Smad3 effectively blocked MNT in vivo, which may serve as a druggable target for suppressing neurogenesis in lung carcinoma." (PMID 36206343, 2022). "Moreover, the actin binding protein profilin-2 interacts with HDAC1 to inhibit its binding to the promoters of Smad2 and Smad3, leading to Smad protein activation and subsequently enhancing the TGF-β-induced EMT and angiogenesis in lung cancer cells." (PMID 33803458, 2021).
lung carcinoma (continued). "The result shows miR-216b introduction downregulates Smad3, increases BCL-2 level, induces chemoresistance to carboplatin with an increase in IC50, and decreases apoptosis, indicating that miR-216b is a potential upstream regulator of BCL-2 in lung cancer." (PMID 32668597, 2020). "SMAD3 and PAX6 were upregulated in lung cancer tissues and cancer cells." (PMID 30594196, 2018). "Based on these findings, inhibiting SMAD3 and PAX6 should be further explored and may become a promising mechanism for treating nonsmall cell lung cancer in the future." (PMID 30594196, 2018). "However, TGF-β1/p-SMAD3 pathway is considered to be a canonical pathway inducing EMT in many tumors, including lung cancer." (PMID 27992365, 2017). "TGF-β-induced CD59 expression during EMT is dependent on Smad3 but not on Smad2 in lung cancer A549 cells." (PMID 27548154, 2016). "Interestingly, the expression of SMYD2 and SMAD3 was increased in In-H1299 cells, suggesting that SMYD2 may be related to the metastatic signature of invasive lung cancer." (PMID 37121971, 2023). "In line with this notion, both genetic deletion and pharmacologic inhibition of Smad3 resulted in enhanced N1 development of mouse bone marrow-derived neutrophils (BMDNs) stimulated with LLC cancer cell conditioned medium (LLC-CM) in vitro, arguing that Smad3 restricts TAN maturation in lung cancer." (PMID 37002229, 2023). "Therefore repressing Smad2, Smad3, and Smad4 nuclear translocation may regulate EMT-related TGF-β and suppress metastasis and tumor growth in lung cancer." (PMID 32405368, 2020). "However, it should be noted that Smad3 knockout NK cell therapy did slightly enhance the accumulation of MDSC and Treg cells in LLC tumor, which indicated NK-derived GM-CSF may induce moderate immunosuppression in lung carcinoma." (PMID 38878186, 2024). "Moreover, in the TCGA data, we found upregulation of SMAD3 in lung cancer samples compared to normal samples, as shown by SMYD2 upregulation, suggesting that SMAD3 regulation by SMYD2 could regulate lung cancer metastasis." (PMID 37121971, 2023). "To further clarify the role of USP9X in lung cancer radioresistance and confirm whether this effect is dependent on KDM4C, we transfected exogenously expressed KDM4C into USP9X-depleted cells and found that TGF-β2, p-Smad2 and p-Smad3 protein levels were decreased when USP9X was knocked down." (PMID 33558705, 2021). "Transcriptomic data from METex14Del-expressing cells, stimulated or not by HGF, were mapped onto this lung cancer reference network and revealed activation of a major regulatory node composed mainly by the highly influential transcription factors ETS1, FOSL1 and SMAD3." (PMID 41184222, 2025). "Furthermore, phosphorylation levels of SMAD3 in CD3, CD8, Foxp3, and CD68 cells in non-small cell lung cancer negatively impact the overall and partial disease-free survival in lung cancer patients, independent of histological subtype." (PMID 37685308, 2023). "The silencing of HSP27 enhances an additive effect with TGF-β1-induced EMT and the TGF-β1-induced HSP27 increase is not affected by the suppression of Smad2 and Smad3 in A549 cells, which suggests that HSP27 is involved in TGF-β1-induced EMT in a Smad-independent manner in lung cancer cells." (PMID 29062135, 2017).
hepatocellular carcinoma (89 papers, 2011 to 2025). A malignant tumor that arises from hepatocytes. "The SMAD3 signature was also associated with epithelial–mesenchymal transition (EMT) in hepatoma (Fig EV4B and C)." (PMID 33724679, 2021). "In this study, high level of TGF‐β1 was observed in the biopsies of cancer patients with hepatoma, which was associated with Smad3 hyperactivation but Smad7 reduction in the TME." (PMID 34514726, 2021). "This study demonstrates that elevated N‐acetyltransferase 10 (NAT10) expression stabilizes SMAD3 mRNA through ac4C modification, promoting the progression of hepatocellular carcinoma (HCC)." (PMID 41476650, 2025). "It was found that there is abundant SMAD3 in the peripheral blood EVs of patients with hepatocellular carcinoma." (PMID 39501131, 2024). "For example, in vitro experiments have confirmed that SMAD3 promotes the adhesion of hepatocellular carcinoma cells." (PMID 39501131, 2024). "Its content is positively correlated with disease stage and pathological grade, and negatively correlated with disease-free survival after surgery in hepatocellular carcinoma patients and SMAD3 expression in primary tumors." (PMID 39501131, 2024). "Conversely, the decreased levels of p‐Smad1/5/8 and Smad6 following the increased level of p‐Smad3 were abolished in the HUVECs pre‐incubated with BMP9‐overexpressing HBV‐infected hepatoma cells." (PMID 37132170, 2023). "A significant decrease in the p‐Smad1/5/8 and Smad6 levels following the increase in the p‐Smad3 level was detected in the HUVECs pre‐incubated with HBV‐infected hepatoma cells compared with those pre‐incubated with HBV‐uninfected hepatoma cells." (PMID 37132170, 2023). "XCT expression was repressed by TGF-β1 by activating Smad3 and enhancing lipid peroxidation in hepatocellular carcinoma cells." (PMID 35265722, 2022). "These exosomes can induce the enhancement of SMAD3 signal transduction and adhesion ability of the recipient hepatoma cells." (PMID 35812745, 2022). "In hepatocellular carcinoma, miR-708 is involved in cell dissemination through SMAD Family Member 3 (SMAD3) targeting." (PMID 35011736, 2022). "Hepatoma cells release exosomes containing SMAD family member 3 (SMAD3) protein and mRNA and transfer them to isolated hepatoma cells to promote their adhesion." (PMID 35812745, 2022). "GSK-3β can negatively modulate TGF-β/SMAD3 signaling by facilitating SMAD3 deactivation after SMAD3 phosphorylation in HepG2 hepatocellular carcinoma cells." (PMID 36115986, 2022). "It is reported that HEY2 binds to Smad3 and Smad4 promoters to inhibit the transcriptional activity of Smad3 and Smad4, and accelerates the malignant progression of hepatocellular carcinoma through TGF-β/Smad signaling pathway." (PMID 34127651, 2021). "Consistently in the current study, activation of EMT by autophagy was also shown in hepatocellular carcinoma cells, which associated with the activation of TGF-β/Smad3 signaling." (PMID 34497522, 2021). "For example, in liver cancer, starvation-induced autophagy promotes the expression of EMT-related molecular markers through the transforming growth factor β (TGF-β)/Smad3 signaling pathway, thereby enhancing the invasive ability of hepatoma cells." (PMID 34124097, 2021). "It was found that the TGF-β1/Smad3 pathway was activated in hepatoma model, suggesting that the TGF-β1/Smad3 pathway played a significant role in the development of liver cancer." (PMID 34112163, 2021). "In conclusion, TGF-β1 represses xCT expression via Smad3 activation and enhances lipid peroxidation in hepatocellular carcinoma cells with an early TGF-β1 signature, which would benefit from the targeting of GPX4." (PMID 32471991, 2020). "The components of HMOX-1/CO pathway have been shown in hepatocellular carcinoma cells to confer their resistance to TGF-β-mediated growth inhibition by increasing Smad3 phosphorylation via the ERK1/2 pathway." (PMID 32408627, 2020).